KLK7 (kallikrein related peptidase 7)
Diseases named in the same sentence as KLK7 in open-access papers (continued):
Sharing a sentence is not in itself a finding about the gene and the disease.
Sepsis (1 paper, 2022). Sepsis is defined as life-threatening organ dysfunction caused by a dysregulated host response to infection. "Our findings suggest that vaspin can reduce sepsis-induced cardiac inflammation, alleviate sepsis-induced cardiac injury, and improve cardiac function by inhibiting KLK7 expression." (PMID 35873711, 2022). "In summary, our data showed for the first time that vaspin alleviates cardiac inflammation and protects against cardiomyocyte apoptosis by inhibiting KLK7 expression and alleviates sepsis-induced myocardial injury and cardiac dysfunction." (PMID 35873711, 2022). "Vaspin alleviates cardiac inflammation and plays a protective role in sepsis-induced cardiac injury by reducing KLK7 expression." (PMID 35873711, 2022). "Therefore, the regulatory effect of vaspin on sepsis progression was examined in KLK7-/- mice." (PMID 35873711, 2022).
skin cancer (1 paper, 2017). "We found multiple UV target genes to be critical to the survival of skin cancer cells, including CD200, GJA5, GPR115, KLK7, SLAMF7 and SLP1." (PMID 28211524, 2017).
squamous cell carcinoma (1 paper, 2024). A carcinoma arising from squamous epithelial cells. "For example, KLK7 positivity has been found in 20.0%-92.5% of adenocarcinomas of the endocervix and from 41.0%–100% of squamous cell carcinomas of the oral cavity." (PMID 38961454, 2024). "Desquamation of keratinized cells also occurs in cancers and explains the expression of KLK7 in keratinized squamous cell carcinomas." (PMID 38961454, 2024). "KLK7 expression predominates in squamous cell carcinomas of different organs but is also common in ovarian and biliopancreatic adenocarcinomas as well as adenocarcinomas of the upper gastrointestinal tract." (PMID 38961454, 2024). "A frequent KLK7 expression in squamous cell carcinomas of various sites was expected based on the function of the protein in the desquamation of corneocytes." (PMID 38961454, 2024).
squamous intraepithelial lesions (1 paper, 2025). "In this study, we demonstrated that the expression of serine proteases matriptase, KLK5, KLK7, and their inhibitors, HAI-1 and HAI-2, is dysregulated in human biopsies of high-grade squamous intraepithelial lesions (HSIL)." (PMID 40753921, 2025).
thyroid gland disorder (1 paper, 2025). A disease involving the thyroid gland. "We discovered that KLK7 mRNA expression is linked to histological type, pathological stage, pathological T stage, pathological N stage, tumor location, extrathyroidal extension, and a history of thyroid gland disorders." (PMID 39991575, 2025). "Additionally, logistic regression analysis indicated that classical & tall cell types, stages III & IV, T3 & T4, N1, extrathyroidal extension, and no history of thyroid gland disorders are risk factors for high KLK7 mRNA expression in THCA." (PMID 39991575, 2025).
tumor (42 papers, 2005 to 2026). "In CC tissues and serum, kallikrein 7 (KLK7) levels were reported to be higher, both of which are associated with tumor growth, invasion and metastasis." (PMID 36905477, 2023). "In PDAC, an increased KLK7 expression was associated with lower-grade moderate or well-differentiated tumours." (PMID 34439122, 2021). "The combination of KLK5 + KLK7 mRNA was found to be significantly associated with residual tumor mass (p = 0.041), which was previously also observed for KLK5 mRNA alone." (PMID 33087135, 2020). "KLK7 overexpression has also been found to be associated with increased cell proliferation in vitro and increased tumor growth in nude mice." (PMID 26474385, 2015). "We have recently confirmed this finding and also demonstrated that high levels of KLK7 in tumor tissues are associated with chemoresistance in EOC patients." (PMID 24043563, 2014). "Moreover, as a COX-2 associated gene in TNBC, we found KLK5 and KLK7 gene KOs to restore tumor cell sensitivity to celecoxib both in vitro and in vivo." (PMID 33588911, 2021). "Klk7 has been implicated in the cleavage of corneodesmosomal proteins, such as Cdsn and Dsc1, during terminal differentiation of the epidermis, and of Dsg1 in tumor cells." (PMID 32457102, 2020). "During tumor progression, higher levels of KLK7 in tumor tissue have been mainly associated with poor prognosis in a variety of cancer types, even when the expression level was found to be downregulated in relation to the corresponding nonmalignant, normal tissue." (PMID 28636767, 2017). "In addition, high tumor levels of KLK7-IR, were, like KLK6, found to be associated with reduced patient survival." (PMID 26231762, 2015). "In such cancers, KLK7 facilitates tumor spread and metastasis by breaking down components of the extracellular matrix 19-22." (PMID 39991575, 2025). "The experimental results demonstrated that reducing KLK7 expression significantly impaired migration and invasion capabilities, confirming its role as a crucial mediator of tumor progression." (PMID 39991575, 2025). "The results showed a significant reduction in KLK7 expression levels in tumor samples from the KLK7 knockdown group (P < 0.05)." (PMID 39991575, 2025). "Bulk RNA-seq analysis from lesions of transgenic mice expressing oncogenes related to HPV infection revealed that Klk5 and Klk7 regulate Klk14 expression, which activates RhoA and NF-κB signaling pathways, thereby promoting tumor progression." (PMID 40753921, 2025). "KLK7 positivity was found in 64 of 147 tumor categories, including 17 tumor categories with at least one strongly positive case." (PMID 38961454, 2024). "Our successful analysis of 12,345 tumors from 147 entities identified KLK7 expression in 64 cancer categories and enabled a ranking of tumor types according to their KLK7 positivity rate." (PMID 38961454, 2024). "Overall, 64 (43.5%) of 147 tumor categories showed detectable KLK7 expression with 17 (11.6%) tumor categories including at least one case with strong positivity." (PMID 38961454, 2024). "The analysis of the kallikrein-related peptidase family in CRC tumor samples from The Cancer Genome Atlas (TCGA) database identified a distinct pattern of overexpression of KLK6 along with elevated expression of KLK7, KLK8, and KLK10." (PMID 39594797, 2024). "It has been reported that KLK6 and KLK7 cleave E-cadherin to promote tumour cell functions, including cell proliferation, migration and invasion." (PMID 34439122, 2021). "Based on tissue analysis, KLK7 was found in both stromal and tumor cells, whose expression was higher in tumor cells." (PMID 33336051, 2020). "The mRNA expression of KLK7 ranks fifth highest in different tumor cell lines RNA-seq data, which is behind that of upper aerodigestive tract, bile duct, esophagus and colorectal." (PMID 33336051, 2020). "To compare the mRNA expression difference of KLK7 between tumor and normal tissues in multiple cancers, we used the Oncomine database." (PMID 33336051, 2020).
tumor (continued). "KLK7 protein expression data, i.e. antigen levels determined by ELISA in tumor tissue extracts, were available from a previous study analyzing a partially overlapping patient cohort." (PMID 33087135, 2020). "Based on the comparation of the 61 tumor stage and 59 prognosis related DEGs, Kallikrein-related peptidase 7 (KLK7) and KLK 10 were presented in both sets." (PMID 30414611, 2018). "Low expression of KLK7 was observed in the tumor adjacent tissues, whereas in the cancerous tissues, elevated expression of KLK7 up to 30 folds as evaluated by the mean IOD values (P < 0.001 = was noticed." (PMID 29560118, 2018). "For instance, kallikrein genes KLK5, KLK6 and KLK7 were downregulated in HPV16+ tumours and co-expressed with two overlapping antisense transcripts: CTB-147C22.8 and CTB147C22-9, as well as KLK10 with its antisense CTC-518B2.12." (PMID 29263803, 2016). "Kaplan-Meier survival analysis indicated that patients with KLK6-IR < 10, KLK6 percent tumor core stained < 3, or KLK7-IR < 9 had a significantly improved survival." (PMID 26231762, 2015). "Adjusted for residual tumor mass and nuclear grade, KLK7 entered the model as a protective marker (HR, 0.41)." (PMID 25436002, 2015). "Specifically, higher tumor core levels of KLK6, KLK7 and KLK9 were each associated with reduced GBM patient survival." (PMID 26231762, 2015). "The multivariate Cox model for OS contained residual tumor mass, nuclear grade and KLK7 as independent factors." (PMID 25436002, 2015). "In multivariate Cox analysis, only residual tumor mass and, for OS, nuclear grade and KLK7 were of clinical significance." (PMID 25436002, 2015). "We also found that EOC cells derived from ascites fluid expressed higher levels of KLK7 and α5β1 integrin compared to their matched primary tumor cells." (PMID 24043563, 2014). "As KLK4 and KLK7 are up-regulated in EOC cells and tumor tissue samples, with high levels associated with poor outcome in women with this disease [87, 102???], we over-expressed these peptidases in SKOV3 EOC cells to determine their function." (PMID 24043563, 2014). "We previously demonstrated KLK7's tumor-promoting role both in vitro and in vivo, but its role in CRC metastasis remains unclear." (PMID 41335524, 2025). "In cancer, however, KLK7 expression has been described to occur in a broad range of tumor entities." (PMID 38961454, 2024). "Twenty other tumor entities showed—a usually weak—KLK7 positivity in less than 9%." (PMID 38961454, 2024). "This work presented potential agents targeting KLK7 that may providestrategies for treating skin abnormalities." (PMID 38886921, 2024). "Across the six ductal cell subclusters, we observed an opposite trend of gene expression between proliferating markers (e.g., MKI67) and malignant metastatic markers (e.g., CEACAM5/6 and KLK7), suggestive of orchestrated differentiation of tumor cells during metastasis." (PMID 37612267, 2023). "Furthermore, we found MFGE8, KLK5, and KLK7 knockout (KO) to restore celecoxib sensitivity in TNBC cells leading to marked reductions in primary tumor growth." (PMID 33588911, 2021). "Previously determined KLK5 mRNA as well as KLK5 and KLK7 antigen concentrations were used to evaluate the relationship between the expression patterns of both factors on the mRNA as well as protein level in tumor tissue of HGSOC patients." (PMID 33087135, 2020). "KLK7 secreted by tumor cells or added exogenously could promote the degradation of extracellular matrix (ECM) and cellular adhesive molecules (CAMs) such as fibronectin, desmoglein 2, E-cadherin, urokinase-type plasminogen activator receptor." (PMID 29560118, 2018). "The signaling pathways participating in KLK7-mediated effects in tumor cells have not been elucidated, but effects on cell invasion and proliferation may account for the shortened survival times we observe in GBM patients with elevated tumor KLK7 expression." (PMID 26231762, 2015).
tumor (continued). "In addition, we and others have reported that high tumor levels of KLK4 and KLK7 were associated with chemoresistance in patients with this cancer." (PMID 24043563, 2014). "Similarly, the presence of KLK7 on the surface of cancer cells suggests that, by digestion of extracellular matrix, KLK7 helps in the shedding of tumor cells and, therefore, in invasion and early metastasis." (PMID 23319948, 2012). "As reported recently by Ramani and Haun (2008), overexpression of KLK7 in tumour cells may play an important role in tumour invasion through proteolysis of extracellular matrix components, such as fibronectin." (PMID 19367279, 2009). "Consequently, our evaluation indicates that KLK7 could be a dependable indicator for forecasting unfavorable tumor outcomes and reactions to immunotherapy." (PMID 39991575, 2025). "A previous analysis of the kallikrein-related peptidase family in CRC tumor samples from the TCGA database revealed that KLK6 overexpression in human tumors is associated with the overexpression of other members of the kallikreins protease family, i.e., KLK7, KLK8, and KLK10." (PMID 39594797, 2024). "Additionally, RNA sequencing of CRC cells with TRIP13 knockdown identified COL6A3, TREM2, SHC3, and KLK7 as downstream targets that may have functional relevance in TRIP13‐mediated tumor growth and metastasis." (PMID 33037736, 2020). "Furthermore, KLK7 may stimulate tumor cell invasion and metastasis through cleaving extracellular matrix (ECM) proteins and several adhesion molecules, such as desmoglein-1 and desmocollin-1." (PMID 33087135, 2020). "In our study, the cell culture medium from wild type PANC-1 could significantly increase the migration and invasion capacities of KD4 cell, indicating that KLK7 can act as a paracrine factor on other cells located at the tumor microenvironment and regulate the malignant progress of cancer cells." (PMID 29560118, 2018). "Eight genes exhibited greater than 340-fold increases in expression in tumor tissues (CLDN6, KLK7, WNT10A, MYBL2, MAL2, KRT7, PRSS8, EPCAM; Median (Range) of fold increase = 344 (261–7267))." (PMID 41465326, 2025). "The differential gene expression levels between the tumor and adjacent tissue showed that KLK6 and KLK7 expression levels were higher in normal tissues than in tumors." (PMID 38137332, 2023). "ROBO1, KLK6, LIMK2, KLK7, NLGN4X, MBP, and NEDD9 expression levels were significantly higher in normal tissues than in tumors, demonstrating the possibility of being a tumor suppressor gene." (PMID 38137332, 2023). "A growing body of evidence suggests tumor-supporting roles of several members of the kallikrein-related peptidase (KLK) family, including KLK5 and KLK7, in this cancer subtype." (PMID 33087135, 2020). "In this study, KLK7 and KLK10 were identified as the biomarkers of tumor stage and prognosis of PTC, which were consistent with the previous report." (PMID 30414611, 2018). "These KLK4–7 expressing OV-MZ-6 cells increased tumor growth in an animal model compared to OV-MZ-6 cells expressing the single KLK4, KLK5, KLK6 or KLK7, or vector controls." (PMID 24043563, 2014). "No notable correlation was observed among KLK7 mRNA expression and age, gender, pathological M stage, primary tumor type, or residual tumor." (PMID 39991575, 2025). "Conversely, genes implicated in tumor progression, including Arghef18 and NfκB1, were downregulated in HPV transgenic mice lacking Klk5 and Klk7." (PMID 40753921, 2025). "For this purpose, KLK7 expression was analyzed in more than 13,000 tumor tissue samples from 147 different tumor types and subtypes as well as 76 non-neoplastic tissue categories by immunohistochemistry (IHC) in a tissue microarray (TMA) format in this study." (PMID 38961454, 2024). "Existing RNA data, along with our IHC results, do not suggest a high frequency of high KLK7 expression levels in these tumor entities." (PMID 38961454, 2024).
tumor (continued). "Many important tumor entities such as carcinomas of the lung, stomach, esophagus, liver, bile ducts, or the endometrium have not been analyzed for KLK7 expression yet." (PMID 38961454, 2024). "Comparing the bulk transcriptome profiles of the TD and nonTD patients, the TD patients exhibited upregulation of keratins (KRT81, KRT6B, KRT15, KRT5) and kallikreins (KLK5, KLK6, KLK7), indicating active extracellular matrix (ECM) remodeling and tumor expansion." (PMID 39664386, 2024). "Fifty of the 64 tumor categories with at least occasional KLK7 expression had not been studied by IHC before." (PMID 38961454, 2024). "The differential gene expression levels between the tumor and adjacent tissue indicated that the ROBO1, KLK6, LIMK2, KLK7, NLGN4X, MBP, and NEDD9 gene expression levels were higher in normal tissues than in tumors; however, EFNA1 was higher in the tumor than the normal ones." (PMID 38137332, 2023). "Briefly, scrambled, MFGE8, KLK5, and KLK7 KO cells generated in the MDA-MB-231 background were transplanted into the mammary fat pad of NSG mice (1 × 106 cells per mouse) and allowed for orthotopic tumor growth." (PMID 33588911, 2021). "Strikingly, both M74‐D6 and M74‐H cells overexpressing KLK7 displayed an elongated and irregular morphology with membrane protrusions typical of invading tumor cells not seen in M74‐mock cells." (PMID 28636767, 2017). "Moreover, KLK7 has been reported as an activator of matrix metalloproteinase-9 (MMP-9) in carcinomas, thus displaying a key role in processes of tumor cell migration, invasion, and angiogenesis, further implying the involvement of KLK7 in tumor progression." (PMID 33087135, 2020). "The mean percent tumor core stained for KLK1, KLK7, KLK9 or KLK10 across grades III and IV were not significantly different." (PMID 26231762, 2015). "KLK6, KLK7 and KLK 9 were abundant in the conditioned medium from ascites derived tumor cells, OVCAR3 and CaOV3, but not in ES2 cell conditioned media." (PMID 18560578, 2008).